HIF1A (hypoxia inducible factor 1 subunit alpha)
Diseases named in the same sentence as HIF1A in open-access papers (continued):
Sharing a sentence is not in itself a finding about the gene and the disease.
breast cancer (continued). "To confirm that HIF1A-mediated PTK2 transcription is critical for breast cancer cell to survive anoikis, we examined the effect of HIF1A knockdown on cell sensitivity to anoikis and detachment-induced activation of PTK2, ERK, and AKT." (PMID 27495308, 2016). "In breast cancer cohort, mean HIF-1α plasma levels was 10.197ng/dl (95% CI 9.984-10.409), while the mean of PGC-1α plasma levels was 246.502ng/dl (95% CI 236.606-256.400)." (PMID 27780920, 2016). "SMARCE1 plays an essential role in breast cancer metastasis by protecting cells against anoikis through the HIF1A/PTK2 pathway." (PMID 27495308, 2016). "In the breast cancer cohort, we compared plasma level of HIF-1α with the clinicopathologic features, including the common survival predictors." (PMID 27780920, 2016). "Breast cancer patients had significantly higher HIF-1α and PGC-1α levels, which correlated with clinicopathological features, overall with more aggressive cancer characteristics." (PMID 27780920, 2016). "Its related demethylase, JMJD2C (i.e., KDM4C), is found to be upregulated by HIF-1α and it can serve as a co-activator for HIF-1α which epigenetically modulates metabolic reprogramming and metastasis in breast cancer cells by decreasing H3K9me3 as well." (PMID 26861406, 2016). "Our results suggest that the therapeutic implications of HIF-1α and Axl co-expression in breast cancer should further be explored." (PMID 26760782, 2016). "Our results suggest that breast cancer tumorigenicity can increase due to metabolic reprogramming and HIF-1α-dependent signaling." (PMID 27058900, 2016). "During the two weeks of daily oral digoxin therapy, researchers will measure, by immunohistochemistry, the expression of HIF1A protein in surgically resected breast cancer tissues." (PMID 26859576, 2016). "Recently, several studies have demonstrated that metformin inhibits HIF-1α expression in patients with breast cancer or hepatocellular carcinoma Bel-7402/5-fluorouracil (Bel-Fu) cells." (PMID 26621849, 2016). "The data suggest that breast cancer patients with high HIF-1α plasma levels express more aggressive cancer characteristics and advanced stages." (PMID 27780920, 2016). "Accordingly, we show here that a positive correlation of MCU expression with HIF1A and its regulated genes exists in human breast cancer samples, indicating that, in parallel with HIF‐1α, MCU represents a novel marker of cancer progression." (PMID 27138568, 2016). "This study establishes a novel role of SMARCE1 in regulating metastatic potential of breast cancer cells by promoting survival of detached cells through the HIF1A/PTK2 pathway." (PMID 27495308, 2016). "In this study, we demonstrated that SMARCE1 plays a key role in breast cancer metastasis by protecting breast cancer cells against anoikis through the HIF1A/PTK2 pathway." (PMID 27495308, 2016). "Our data suggest that mitochondrial adaptation to DKG elevates the ratio of succinate or fumarate to α-KG, which in turn stabilizes HIF-1α and reprograms breast cancer cells into a stem-like state." (PMID 27058900, 2016). "Disease free and overall survival of breast cancer patients with high HIF-1α and PGC-1α were significantly poorer than in patients with low plasma levels." (PMID 27780920, 2016). "High HIF-1α expression is significantly associated with Axl and VEGF expression, and with markers of poor prognosis in this series of breast cancer, suggesting HIF-1α and Axl as potential therapeutic targets in African breast cancer." (PMID 26760782, 2016). "More recently, we demonstrated that PEITC decreased HIF1α protein expression via inhibition of HIF1A mRNA translation in MCF7 breast cancer cells." (PMID 27579538, 2016). "Lastly, murine mammary carcinoma (EMT-6) cells that were treated with porfimer sodium-PDT exhibited HIF-1α stabilization and its consequent translocation to the nucleus." (PMID 26657503, 2016).
breast cancer (continued). "HIF-1α promotes hypoxia-induced breast cancer progression and metastasis through the direct activation of TWIST expression." (PMID 25885919, 2015). "Selective silencing of HIF-1α expression in mouse mammary epithelium and mouse breast cancer models led to failed lactation and increased tumour growth and metastasis, respectively." (PMID 25955753, 2015). "In spite of many attempts where the role of either IL-1β or HIF-1α was evaluated, detailed mechanisms for their effects on breast cancer cell migration under hypoxia are still unclear." (PMID 26696754, 2015). "In a mammalian example, hypoxia induces lipid droplets in glioblastoma and breast cancer cells via a pathway involving HIF-1α." (PMID 26451484, 2015). "In a study with MDA-MB-435 breast cancer cells, it was found that only HIF-1α was essential for hematogenous metastasis to the lungs, with no apparent role for HIF-2α, suggesting a differential role of HIF isoforms in the metastatic process." (PMID 26305551, 2015). "Collectively, our findings underline the role of HIF-1α and NFκB in the complexity of migration program of MDAMB231 breast cancer cells in the presence of IL-1β under hypoxic conditions." (PMID 26696754, 2015). "In fact, this had been elegantly demonstrated through the preferential expression of HIF-1α in peri-necrotic/peri-fibrotic tumor cells in TNBC and BRCA1 mutated breast cancers." (PMID 26046764, 2015). "Our observations consisted with previous findings that Sp1 was being involved in the basal transcriptional activation of HIF-1α in breast cancer cells." (PMID 26640316, 2015). "In breast cancer cells, antiangiogenic factors increase the population of CSCs by generating intratumoral hypoxia mediated by HIF1α." (PMID 26372732, 2015). "In the present study, we show that OA inhibits glycolysis in breast cancer cells through SIRT3-mediated HIF1α destabilization, which has important implications for treatment of cancers." (PMID 25855962, 2015). "Clinically, miR-373 is negatively associated with TXNIP and positively associated with HIF1α and TWIST, and activation of the miR-373-TXNIP-HIF1α-TWIST signaling axis is correlated with a worse outcome in patients with breast cancer." (PMID 26196741, 2015). "Except for LOXL4, all enzymes of the LOX family, as well as HIF-1α, were upregulated in breast cancer samples." (PMID 26265048, 2015). "Continuous chemotherapy treatment of TN breast cancer cells has also been shown to drive hypoxia inducible factor-1α (HIF-1α) expression, a critical determinant of cancer stemness." (PMID 26141457, 2015). "Here, we show that oroxylin A inhibits glycolysis in breast cancer cells via the Sirtuin 3 (SIRT3)-mediated destabilization of hypoxia-inducible factor 1α (HIF1α), which controls glycolytic gene expression." (PMID 25855962, 2015). "In breast cancer, patients with a diffuse HIF-1α staining pattern have been demonstrated to have a significantly better prognosis than patients with perinecrotically overexpressed HIF-1α." (PMID 25789026, 2015). "Overexpression of the receptor tyrosine kinase HER2/neu (ErbB2) in breast cancer, led to increased HIF-1α expression, increased ERK and Akt activities, reduced Bim expression and resistance to anoikis." (PMID 26405162, 2015). "Both LOXL4 and HIF-1α mRNA levels were significantly higher in this breast cancer patient group than in ER-positive samples." (PMID 26265048, 2015). "We measured levels of hypoxia-inducible factor (HIF)-1α in 52 primary breast cancer patients before and after receiving neoadjuvant endocrine therapy with letrozole for at least 3 months." (PMID 25929338, 2015). "In summary, TNBC samples displayed higher HIF-1α expression levels than other breast cancer samples." (PMID 26265048, 2015). "The hypoxia-inducible transcription factor subunits HIF-1α and HIF-2α are associated with breast cancer metastasis and poor patient survival." (PMID 25955753, 2015).
breast cancer (continued). "Our study showed that inhibition of HIF-1α by zoledronic acid improved the sensitivity to endocrine therapy in breast cancer." (PMID 25929338, 2015). "This is in contrast to the breast cancer MCF7 cell line in which HIF-1α is expressed only under hypoxia." (PMID 26393682, 2015). "The data suggest that adipocytes co-cultured with cancer cells downregulate ER gene expression and promote epithelial-mesenchymal transition (EMT) in breast cancer cells through upregulation of HIF1α." (PMID 25823469, 2015). "In conclusion, the findings of this study suggest that HIF-1α is a crucial determinant of endocrine resistance in human breast cancer." (PMID 25929338, 2015). "In this study, we report that NCOA1 works with transcription factors HIF1α and AP-1 (c-Jun/c-Fos) to promote VEGFα expression in breast cancer cells and drive breast tumor angiogenesis in both mouse and human breast tumors." (PMID 26287601, 2015). "In the metastatic breast cancer cells, HIF-1α levels increased from 7% (CN) to 100% (CH) (a 14-fold increase) when control-normoxia (CN) cells were compared to control-hypoxia (CH) cells." (PMID 26536104, 2015). "Other investigators have shown that ERα gene expression and protein levels are downregulated by HIF1α when breast cancer cells are cultured under hypoxic conditions." (PMID 25823469, 2015). "HIF-1α plays critical roles in tumor angiogenesis and metabolic reprogramming, as well as multiple steps in the process of breast cancer invasion and metastasis." (PMID 26059435, 2015). "Recent study has indicated that ROS-stimulated HIF-1α accumulation is related to PI3K/AKT activation in hypoxic MCF-7 breast cancer cells." (PMID 26193287, 2015). "HBXIP disassociates the interaction of HIF1α with pVHL, resulting in the increase of stability of HIF1α in breast cancer." (PMID 26309161, 2015). "Here, we observed that in normal breast and breast cancer derived cell lines, HIF1A mRNA expression can decrease by 50 to 80% after 8 hours of hypoxic exposure." (PMID 26647819, 2015). "Our data show that HBXIP promotes the glucose metabolism reprogramming through downregulating SCO2 and PDHA1 in breast cancer cells, involving HIF1α/miR-183/96/182 cluster/pVHL signaling." (PMID 26309161, 2015). "Our data support a notion of potential double prognostic meaning of HIF-1α expression in breast cancer and necessitate focused studies taking into account the latent immunophenotype interactions and tissue heterogeneity aspects." (PMID 26512778, 2015). "Aminoflavone, a ligand of the aryl hydrocarbon receptor, is known to repress HIF-1α translation in human breast cancer cells by inducing eIF2α phosphorylation." (PMID 26474388, 2015). "Breast cancer cells were transfected with stealth RNA oligonucleotides targeted to human HIF-1α mRNA (HIF-1α siRNA)." (PMID 26696754, 2015). "Balaji Krishnamachary etc. showed HIF-1α was a regulator of CD44 expression in breast cancer cells under hypoxic conditions." (PMID 26323509, 2015). "Our co-immunoprecipitation assay also demonstrated that NCOA1 forms a protein complex with HIF1α in MDA-MB-231 breast cancer cells." (PMID 26287601, 2015). "Human breast cancers with high levels of HIF-1α contain elevated OGT, and lower OGA levels correlate independently with poor patient outcome." (PMID 26640316, 2015). "Unlike the case for murine embryonic fibroblasts (MEFs), HepG2 human hepatic carcinoma cells and MCF-7 human breast cancer, HIF-1α was notably elevated in RCC4 cells, even under normoxic conditions, and was prominently localized in the nucleus." (PMID 26474388, 2015). "In brain and breast cancers, HIF-1α overexpression increases angiogenesis by upregulating the levels of VEGF, interleukin-8, and basic fibroblast growth factor." (PMID 26528854, 2015). "The role of HIF-1α in endocrine resistance of breast cancer cells was further investigated by shRNA-mediated knock down of HIF-1α expression in MCF-7/hyp cells." (PMID 25929338, 2015).
breast cancer (continued). "Nicely fitting with these observations, the present data reveal that copper induces the expression of GPER through HIF-1α, leading to the regulation of VEGF in breast cancer cells and cancer associated fibroblasts (CAFs)." (PMID 26415222, 2015). "One such gene is DDX3, a member of the RNA helicase family, which we have shown to be dysregulated in breast cancer cell lines, up-regulated by HIF-1α, and involved in cancer maintenance and metastasis." (PMID 25820276, 2015). "One possibility is that increased HIF-1α expression facilitates endocrine resistance of breast cancer cells due to accelerated proliferation of the uncontrolled cancer cells and a lack of blood supply." (PMID 25929338, 2015). "One clinical trial is currently recruiting patients with breast cancer to receive digoxin prior to surgery to block HIF-1α and potentially thwart cancer cell growth." (PMID 26046764, 2015). "It has been reported that bisphosphonate acids, such as zoledronic acid, inhibit expression of HIF-1α in breast cancer cells." (PMID 25929338, 2015). "Our co-culture and siHIF1α transfection data suggest that HIF1α generated from adipocytes co-cultured with MCF-7 cells downregulated ER gene expression in the breast cancer cell line." (PMID 25823469, 2015). "Blocking the PI3K/Akt/mTOR pathway (which indirectly activates HIF1α), with the inhibitor, temsirolimus has shown promise in vitro and in phase II clinical trials against breast cancer." (PMID 26501324, 2015). "The enhanced mammosphere formation and Aldefluor+ cell content observed in breast cancer cells relies on hypoxia-inducible factor 1α (HIF1α)." (PMID 26372732, 2015). "HIF-1β protein was expressed in 32.0% of HIF-1α(+), and in (44.3%) of HIF-1α(-) breast cancer cases (p = 0.033; χ2 test)." (PMID 26046764, 2015). "In vitro studies revealed that CSC increase in breast carcinoma xenografts due to anti-angiogenic treatment (Sunitinib and Bevacizumab) followed by hypoxic conditions is primarily mediated by HIF-1α (EMT induction)." (PMID 26210994, 2015). "EGCG, constituent of green tea, significantly shows a role in the inhibition of VEGF expression by suppressing the activation of HIF-1α and NF-κB pathways, thereby inhibiting tumor growth, proliferation, migration, and angiogenesis of breast cancer." (PMID 25977926, 2015). "Here we report evidence that miR-18a plays an important role in restricting tumor growth and pulmonary metastasis of basal-like breast cancer by regulating HIF1A expression and hypoxic response." (PMID 25069832, 2014). "They further showed that HIF1α, a known mediator of radioresistance in breast cancer, activates the EZH2 gene and increases EZH2 expression under hypoxic conditions." (PMID 25051981, 2014). "In breast cancer, HIF1α overexpression can be detected in ductal carcinoma in situ, the pre-invasive stage at which angiogenesis is first induced." (PMID 24567056, 2014). "Taken together, these observations provide additional evidence that supports a conserved role for miR-18a in limiting HIF1A activity in basal-like breast cancer cells." (PMID 25069832, 2014). "To validate this observation we performed immunohistochemical analysis of human breast cancer specimen using HIF-1α as a marker for designating hypoxic regions." (PMID 25051364, 2014). "In this study, we investigated the function of miR-18a in regulating breast cancer metastasis through the hypoxia-inducible factor 1α (HIF1A)–dependent hypoxic response." (PMID 25069832, 2014). "In contrast, the less metastatic breast cancer cell T47D showed very weak HIF-1α expression and LOX release by hypoxia." (PMID 25238333, 2014).
breast cancer (continued). "In breast cancer, hypoxia and HIF-1α have a pivot role in promoting tumor growth and metastasis through the maintenance, expansion as well as increased activity of breast CSCs." (PMID 25269858, 2014). "Inhibition or upregulation of HIF-1α affects breast cancer cell expression of BCRP; AI responsiveness; and expression of cancer stem cell characteristics, partially through BCRP." (PMID 24472707, 2014). "Next, we assessed the effect of DKG and compared it, side by side, with Octyl-2KG on the regulation of HIF-1α abundance in breast cancer MDA-MB-231 cells." (PMID 25420025, 2014). "Treatment with 150 μM CoCl2 induced a hypoxic response in +SA mammary tumor cells as evidenced by a large increase in HIF-1α levels, and combined treatment with compound 44 attenuated this response." (PMID 25140303, 2014). "The highly metastatic breast cancer cells MDA-MB-231 induced HIF-1α expression in a time-dependent manner with peak levels observed at 8 h, whereas the less metastatic breast cancer cells MCF-7 showed a weak induction of HIF-1α compared with MDA-MB-231 cells." (PMID 25238333, 2014). "A recent study describing a role for ARRB1 in HIF1A-dependent VEGFA expression in breast cancer cells supports our findings." (PMID 24837709, 2014). "Dose- and time-dependent studies were conducted to determine the effects of CoCl2 treatment on HIF-1α levels in +SA mammary tumor cells." (PMID 25140303, 2014). "In agreement with this study, co-culture of breast cancer spheroids with wild type or HIF-1α knocked out macrophages revealed an indispensable role of macrophage-expressed HIF-1α in tumor angiogenesis." (PMID 24634660, 2014). "The overexpression of FASN in cancer cells has been reported to be regulated by a single oncogene, Akt, and HER-2 pathways through the hypoxic-inducible factor-1α (HIF-1α) in breast cancer cells." (PMID 25255125, 2014). "Of note, LKB1 is required for angiogenesis in endothelial cells, and it is therefore possible that STATs and HIF1α together control the transcriptional activity of LKB1 in breast cancer cells under certain conditions." (PMID 24913037, 2014). "Stable expression of dominant negative HIF-1α (dnHIF) in MDA-MB-231 breast cancer cells, that ablated endogenous HIF-1 transcriptional activity, was validated by western blot and functionality was assessed by HIF-1α activity assay." (PMID 25128202, 2014). "Recently, a study showed that serum HIF-1α levels in diabetic patients with breast cancer were significantly higher than in the normal population." (PMID 24564828, 2014). "The relationship between expression levels of HIF-1α and survival of breast cancer patients has been investigated." (PMID 25302049, 2014). "We demonstrated that P-cadherin overexpression was significantly associated with the expression of HIF-1α, GLUT1, CAIX, MCT1 and CD147 in human breast carcinomas." (PMID 25269858, 2014). "Mild hypoxia appeared to elicit expansion of mammary tumor stem cells via a mechanism mediated by HIF1A." (PMID 23423481, 2013). "The present findings indicate that EGCG significantly inhibits VEGF expression by suppressing the activation of HIF-1α and NFκB pathways, thereby inhibiting tumor growth, proliferation, migration, and angiogenesis of breast cancer." (PMID 23638734, 2013). "Recent studies revealed that HIF-1α-induced LOX overexpression promoted the metastasis of breast cancers in a mouse model and was correlated with poor prognosis of ER negative patients." (PMID 23496980, 2013). "In order to validate the role of proteasome degradation in HIF-1α down-regulation caused by EGC, the proteasome inhibitor MG132 was then administrated to breast cancer cells." (PMID 23457597, 2013). "The aim of this study was to investigate the relation between DDX3 and the hypoxic response in human breast cancer in the light of in vitro results pointing to regulation of DDX3 by HIF-1α." (PMID 23696831, 2013).